PIEZO1 (piezo type mechanosensitive ion channel component 1 (Er blood group))
Diseases named in the same sentence as PIEZO1 in open-access papers (continued):
Sharing a sentence is not in itself a finding about the gene and the disease.
tumor (continued). "However, the effects and mechanisms of Piezo1 on tumor cell apoptosis are intricate." (PMID 36230880, 2022). "However, the Piezo1 knockdown in vivo seemed to have a more prominent impact on tumor growth." (PMID 34831037, 2021). "Also, our recent findings emphasized the role of Piezo1 in tumor cell mechanoptosis." (PMID 34589605, 2021). "Thus, Piezo1 overexpression may aggravate the hypoxic state of local tumours and facilitate tumour growth, ultimately accelerating peritoneal implantation and metastasis of GC." (PMID 33439514, 2021). "Furthermore, the tumour-specific inhibitor of PIEZO1 needs to be addressed in future studies." (PMID 32999349, 2020). "Besides in some aggressive cancers Piezo1 is overexpressed, thus, tumor-selective inhibition of Piezo1 may be therapeutically efficient." (PMID 32635333, 2020). "Silencing Piezo1 abolished compression-induced Rho-ROCK activation and tumor progression in this model." (PMID 41779857, 2026). "Within this context, the mechanosensitive ion channel Piezo1 has emerged as a key TME mechanosensor, yet its role in modulating T cell-mediated anti-tumor immunity remains to be fully elucidated." (PMID 41737555, 2026). "Second, formulate personalized treatment regimens by incorporating tumor type, TME stiffness, and Piezo1 expression." (PMID 41607548, 2026). "Here, we engaged the pseudogene DUXAP8 into a feedback loop affecting the HCC indicator Piezo1 and concerning the HCC tumor microenvironment (TME)." (PMID 42278405, 2026). "A comprehensive understanding of the complex interactions between Piezo1 activation and cytokine networks in different TME cell populations is therefore essential for developing innovative and effective anti-tumour therapeutic strategies." (PMID 41437911, 2026). "We show that acute compressive forces engender epigenetic mechanical memory via Piezo1-activated Rho-ROCK signaling, promoting tumor growth in vivo." (PMID 41779857, 2026). "The high stiffness of the tumour ECM activates Piezo1 in macrophages, triggering the STAT6/PPARγ signalling pathway, which promotes M2 polarization and suppresses anti-tumour immunity." (PMID 41437911, 2026). "These molecules are directly connected to the ECM and the immune microenvironment, suggesting a complex interplay between the Piezo1/ITGB1 axis and the tumor microenvironment." (PMID 40667648, 2025). "Our study demonstrates that the Piezo1/ITGB1 axis enhances the rapid proliferation and antiapoptotic capabilities of tumor cells through enhancing Ca2+ and modulating key proteins such as YAP, α‐SMA, and so on." (PMID 40667648, 2025). "The Piezo1/ITGB1 axis significantly enhances ECM stiffness and the accumulation of collagen, which is a critical factor in the tumor microenvironment that can promote cancer cell behavior, including proliferation, migration, and invasion." (PMID 40667648, 2025). "This study demonstrates that Piezo1 activation enhances FAK‐YAP‐mediated upregulation of PD‐L1 and CXCL10, thereby promoting an immunotherapy‐responsive tumor microenvironment in NSCLC." (PMID 40583158, 2025). "This highlights Piezo1’s role in ES responses and its interaction with pathways like PI3K/Akt and calcium signaling, which are critical for tumor-suppressive secretome generation." (PMID 39940798, 2025). "Taken together, the activation of Piezo1 promotes PD‐L1 expression and CD8+ T cell infiltration in the liver metastatic TIME, converting it to a “hot” tumor that responds better to anti‐PD‐1/PD‐L1 immunotherapy." (PMID 40583158, 2025). "As a result, the efficiency of stimulus transport to the Piezo1 channel is disrupted, thereby inhibiting the Ca2+-mediated AKT/mTOR pathway, which plays a crucial role in tumor development." (PMID 40061015, 2025). "Inhibition of PIEZO1 or DOT1L diminished stemness properties and tumor growth both in vitro and in vivo." (PMID 41533929, 2025). "Western blot analysis further confirmed PIEZO1 protein overexpression in LIHC and STAD tumor tissues." (PMID 40977743, 2025).
tumor (continued). "In the tumor microenvironment (TME), upregulation of Piezo1 expression correlates with increased T cell infiltration." (PMID 41195420, 2025). "Studies have shown that enhanced matrix stiffness can continuously activate Piezo1, leading to Ca2+ influx, which in turn activates signaling pathways such as Src family kinases and YAP/TAZ, ultimately driving tumor cell proliferation, migration, and invasion." (PMID 41195420, 2025). "The Piezo1/ITGB1 axis forms a positive feedback loop with matrix stiffness, amplifying the mechanosensory capacity of tumor cells and promoting their proliferation and progression." (PMID 40667648, 2025). "The Hippo pathway was discussed widely in all kinds of diseases, especially in carcinogenesis; Piezo1 has been shown to modulate the nuclear translocation of YAP in tumors, thereby facilitating tumor metastasis." (PMID 39328029, 2024). "The positive feedback regulation loop, encompassing membrane morphological alterations, Piezo1/integrin β1 axis, and YAP/Ca2+ signal, reinforces tumor‐targeted delivery." (PMID 39258781, 2024). "Such stimulated Piezo1 allows the influx of Ca2+, enabling translocation to the nucleus of calcineurin-dependent NFAT and driving the downstream expression of tumor-specific CARs." (PMID 38534326, 2024). "Mechanistically, we demonstrated that circZNF800 affected the PIEZO1/AKT axis by sponging miR-139-5p and ultimately acted as a tumor promoter in GBM." (PMID 38324181, 2024). "Hippo pathway inactivation and nuclear translocation of YAP/TAZ are also initiated upon Piezo1 activation, leading to increased cell proliferation in oral squamous cell carcinoma, facilitated by a stiff ECM microenvironment of the tumor." (PMID 38534326, 2024). "In addition, Piezo1 expression may be related to tumor stage, grade, and size." (PMID 38362490, 2024). "In breast cancer cells, mechanical compression activates Piezo1 and RhoA/Src/FAK/ERK signaling, which subsequently enhance tumor cell invasion, matrix degradation, and invadopodia formation." (PMID 37864030, 2023). "And at day 20 after tumor cell implantation, naïve CD45.1+ OTII T cells were isolated from OTII-TCR transgenic mice, labeled with CFSE and transferred into WT and Piezo1-/--bearing tumor recipient mice." (PMID 35993548, 2022). "Herein, we found that the DC mechanical sensor Piezo1 stimulated by mechanical stiffness or inflammatory signals directs the reciprocal differentiation of TH1 and Treg cells in inhibiting tumor growth." (PMID 35993548, 2022). "Piezo1-/- mice had more Foxp3+ Treg cells, fewer IFNγ+ TH1 cells, and normal numbers of TH2, TH17, CD8+T cell, and IFNγ+CD8+T cells in tumor tissue compared with WT control." (PMID 35993548, 2022). "Consistently, Piezo1-/- tumor-bearing mice had more Foxp3+ Treg cells and fewer IFNγ+ TH1 cells in tumor tissue compared with WT control." (PMID 35993548, 2022). "A recent study showed that Piezo1 increases MDSCs infiltration; furthermore, it inhibits intratumoral CD4+ memory T cells and CD8+ T cells accumulation, thereby promoting tumor progression." (PMID 36230880, 2022). "Piezo1 knockdown can reduce the expression of Piezo1 and HIF‐1α in GC cells and omentum metastatic tumour tissues, thereby effectively inhibiting the EMT process of GC cells as well as the peritoneal cavity implantation and metastasis of GC cells in nude mice." (PMID 33439514, 2021). "qRT‐PCR and Western blot assays were used to examine the expression levels of Piezo1, HIF‐1α, VEGF, vimentin and E‐cadherin in peritoneal metastatic GC tumour tissues." (PMID 33439514, 2021). "We also found that both in the central areas and peritumoural areas of peritoneal tumour tissues, CD34‐labelled vascular density was prominently reduced in si‐Piezo1 group than that in control group." (PMID 33439514, 2021).
tumor (continued). "Tumour suppressor genes, including PTEN and NF1, were detected at high amplification peaks with high PIEZO1 expression." (PMID 32999349, 2020). "The mRNA expression of PIEZO1 and 2 was clearly decreased in NSCLC tumor tissue compared with that in matched adjacent non-tumor tissue." (PMID 30745454, 2019). "Knockdown of PIEZO1 or PIEZO2 in NSCLC cells significantly promoted cell migration in vitro and tumor growth in vivo." (PMID 30745454, 2019). "The analysis indicated that mRNA expression of PIEZO1 and 2 in NSCLC tissues was significantly lower than that in non-tumor tissues (P<0.0001)." (PMID 30745454, 2019). "In ductal but not lobular tumors, significant inverse correlations were observed between the tumor levels of miR-10b and miR-30c and the mRNA levels of cancer-relevant target genes SRSF1, PIEZO1, MAPRE1, CDKN2A, TP-53 and TRA2B, as well as tumor grade." (PMID 30658617, 2019). "Notably, Piezo1 decodes spatiotemporally specific mechanical stimuli within the TME, influencing malignant phenotypes such as abnormal tumour vasculature, immune evasion and metabolic reprogramming." (PMID 41437911, 2026). "However, within the TME, matrix stiffness may induce endothelial cell contraction through Piezo1 activation, increasing vascular permeability to facilitate tumour cell metastasis while simultaneously forming a physical barrier that limits T cell infiltration into tumour tissue." (PMID 41437911, 2026). "Piezo1 is a non-selective cation channel that plays a crucial role in the cardiovascular, pulmonary, tumor, and immune systems." (PMID 41507149, 2026). "In particular, no redistribution of Piezo1 to the plasma membrane was detected in normal cells upon treatment, unlike tumor cells." (PMID 40060768, 2025). "Surprisingly, western blot results showed increased Piezo1 expression in tumor cells upon ultrasound treatment but not in normal cells." (PMID 40060768, 2025). "PIEZO1 showed predominantly cytoplasmic localization, with significantly lower expression in tumor tissues compared to adjacent non-malignant tissue (p < 0.0001)." (PMID 40724850, 2025). "The Piezo1/ITGB1 axis activates the release of Ca2+ influx, which in turn enhances YAP signaling and its translocation into the nucleus, promoting ECM remodeling and tumor stiffness." (PMID 40667648, 2025). "In contrast, analysis of the TCGA dataset revealed significantly higher PIEZO1 mRNA levels in tumor tissues compared to non-tumorous counterparts." (PMID 40724850, 2025). "Notably, the Piezo1/ITGB1 axis was predominantly localized in CAFs and epithelial cells, suggesting a key role in establishing the relationship between the tumor and the ECM." (PMID 40667648, 2025). "In our study of ccRCC, we observed cytoplasmic expression of PIEZO1 in both tumor cells and adjacent non-tumorous renal tubules." (PMID 40724850, 2025). "Fifth, qRT-PCR and WB validated PIEZO1 overexpression in LIHC and STAD tumor specimens." (PMID 40977743, 2025). "As ECM stiffness generally regulates tumor progression through its receptors, we systematically screened several common ECM-sensing receptors (ITGB1, CD44, Piezo1, Piezo2, YAP1, Syndecan1, and DDR1) via siRNA knockdown, and confirmed the knockdown efficiency by conducting qRT-PCR analyses." (PMID 40685383, 2025). "Immunofluorescence confirmed stable expression of melanocytic marker Melan-A across all groups, indicating that PIEZO1 or DOT1L knockdown did not alter the lineage identity of the tumor cells." (PMID 41533929, 2025). "Furthermore, IFP is also critical in the activation of specific signaling pathways that drive tumor progression and metastasis, including the FAK-ERK1/2 signaling pathway and the PIEZO1-Src-YAP axis." (PMID 39849659, 2025).
tumor (continued). "Furthermore, the expression of PIEZO1 upregulates the MMP, MAPK, and PI3K pathways, thereby influencing tumor initiation and progression." (PMID 40535121, 2025). "We argue that the functional interplay between Piezo1, TRPV4 and TRPC1 might have a pathophysiological relevance in PDAC and other tumor entities." (PMID 40019468, 2025). "Furthermore, Piezo1 may regulate gene expression patterns associated with the TME, thereby influencing the balance between epithelial cell proliferation and apoptosis, disrupting the integrity of tissue barriers, and promoting the aberrant reorganization of tumor vasculature." (PMID 40821847, 2025). "In summary, the Piezo1/integrin β1 signaling axis orchestrates a positive feedback loop that strengthens the tumor‐targeted delivery of arginine‐rich peptides and offering novel insights for cancer diagnosis and treatment." (PMID 39258781, 2024). "In Gudipaty’s work, they found stretching leads to cell division and crowding leads to extrusion, which can help determine how Piezo1 differentially interprets crowding versus stretching to become a tumor suppressor or not." (PMID 39682291, 2024). "While Piezo1 deletion from DCs led to decreased anti-tumor immune response due to the inhibition of TH1 generation and an increase in the production of Treg cells, Piezo1 activation by mechanical stiffness induced proinflammatory responses from DCs via activation of the downstream Hippo pathway." (PMID 38534326, 2024). "Low-frequency ultrasound (33 kHz) suppresses the growth and induces apoptosis of tumor cells by up-regulating Piezo1 but has minimal effects on normal cells." (PMID 37864030, 2023). "Significantly, in the early stages of tumour development, both NFKB1/RELA and PIEZO1 displayed heightened expression levels, paralleled by similar kinetic trends of proliferation‐associated genes such as CDK6, CCND1 and CCND3, as unveiled by functional pseudotime analysis of the scRNA‐seq dataset." (PMID 37983931, 2023). "More importantly, the Anti‐PIEZO1‐MMAE can significantly suppress tumor progression in ESCC xenograft tumor models without any obvious side effects." (PMID 35608274, 2022). "Moreover, Piezo1 is involved in focal adhesion assembly and in the activation of the integrin-FAK pathway, providing a mechanistic explanation for its anti-tumor activity." (PMID 35454942, 2022). "Knockdown of Piezo1 in HCCLM3 and Hep3B cells significantly restrained proliferation, migration, invasion and epithelial–mesenchymal transition (EMT) of HCC cells in vitro, and tumor growth, metastasis, EMT in vivo." (PMID 35461277, 2022). "Both ECM itself and ECM stiffening-induced mechanical stimuli may activate cell membrane receptors and mechanosensors such as integrin, Piezo1 and TRPV4, thereby modulating the malignant phenotype of tumor and stromal cells." (PMID 35331296, 2022). "The mRNA expression of Piezo1 and Piezo2 is significantly lower in tumor tissues of non-small cell lung cancer (NSCLC) than in neighboring nontumor tissues." (PMID 36615408, 2022). "The yes-associated protein (YAP) signaling cascade, which is regulated by Piezo1 during the differentiation of human neural stem cells and the development of zebrafish hearts, is also upregulated by Piezo1/MAPK signaling pathway, thereby promoting tumor cell proliferation." (PMID 36230880, 2022). "Piezo1, HIF-1α, and VEGF are highly expressed in tumor tissues." (PMID 36230880, 2022). "As expected, Piezo1 mRNA was shown to be significantly higher in tumor tissues than non-tumor tissues (n = 20)." (PMID 35942515, 2022). "Interestingly, both Piezo1 and Piezo2 are downregulated in non-small cell lung cancer (NSCLC) tumor tissue compared to matched adjacent normal tissue." (PMID 36158191, 2022). "When the tumor volume reached 300 mm3, the tumor‐bearing mice were divided into three groups with at least five mice per group and treated with PBS, 5‐mg/kg IgG‐MMAE, and 5‐mg/kg Anti‐PIEZO1‐MMAE, respectively." (PMID 35608274, 2022).